CDH1 (cadherin 1)
Diseases named in the same sentence as CDH1 in open-access papers (continued):
Sharing a sentence is not in itself a finding about the gene and the disease.
cancer (continued). "On the other hand, changes in E-cadherin (CDH1) are not consistent with the known changes in the EMT process, since progression of cancer development is accompanied by cell–cell contact inhibition and high invasiveness, resulting from reduced intercellular adhesion." (PMID 40216647, 2025). "Genetic mouse models lacking either CDC20 or CDH1 are lethal, highlighting the necessity of fine dose management should APC inhibitors, such as APCIN and/or TAME, be considered in the future for human cancer therapy." (PMID 38730707, 2024). "Interestingly, while VIM expression was different in cancer types depending on EMT nature, CDH1 expression did not correlate with the EMT nature of the cancers." (PMID 36120580, 2022). "In addition, family members of a CDH1 or CTNNA1 PV index patient, sought genetic and medical counseling, independent of personal cancer history, and were included in this study in case they were diagnosed with the same PV." (PMID 33322525, 2020). "We showed that SNAI2 could recruit EZH2 but not SUZ12, suggesting SNAI1 and SNAI2 have different functions and non-overlapping roles in cancer cells and might cooperate to recruit PRC2 to the CDH1 promoter." (PMID 31938073, 2020). "Moreover, recently published ZEB2 chip-Seq data, using human cancer cell lines, indicated that CDH1 (the E-cadherin gene) was not a target of ZEB2, it was not enriched by ChIP and furthermore, E-cadherin expression was not increased by depletion of ZEB2." (PMID 29963231, 2018). "Moreover, we found a positive correlation between mRNAsi with CDH1 (epithelial marker) and a negative correlation between mRNAsi and CDH2 (mesenchymal marker), suggesting a negative relation between mRNAsi and cancer metastasis in iCCA." (PMID 36712866, 2022). "For modules M3, M4, and M5, although the corresponding GO_BP terms were not directly related to cancer, we found PrCa-relevant genes in these three modules, including BTG2, FOS (also known as c-Fos), and CXCR4 in module M3; ARFGAP3 and CDH1 in module M4; and SMAD3 and MXI1 in module M5." (PMID 25418933, 2014).
infection (237 papers, 2006 to 2026). The state of being infected such as from the introduction of a foreign agent such as serum, vaccine, antigenic substance or organism. "Here, we demonstrate that SP receptor antagonism significantly reduced IEC proliferation (Ki67+ CDH1+), and consequently, infection-induced crypt hyperplasia at 10 dpi compared to infected vehicle-treated mice." (PMID 39937862, 2025). "There was a statistically significant (p < 0.05) difference in the expression of cdh1 for both treatment groups after 12 hpi (hours post-infection) compared to the other timepoints." (PMID 38601152, 2024). "Since mucosoid cultures mimic the gastric epithelium particularly well, Cdh1 cleavage was investigated in mucosoids from different donors after infection with H. pylori wt and H. pylori ∆htrA." (PMID 39000189, 2024). "Correspondingly, the amounts of Cdh1 NTF in the supernatant of H. pylori wt-infected cells increased compared to supernatants of mock-treated cells or after infection with H. pylori ∆htrA." (PMID 39000189, 2024). "We demonstrated that, in addition to modulating CDH1 expression at the transcriptomic level, infection with C. burnetii leads to disruption of E-cad at the cellular surface of BeWo cells." (PMID 37285354, 2023). "Infection-induced crypt hyperplasia was due to increased intestinal epithelial cell proliferation as revealed by significantly increased Ki67+ CDH1+ DAPI+ cells 10- and 29-days p.i.." (PMID 38109366, 2023). "We found that the expression of CDH1/E-cad mRNA was significantly lower in cells infected with SARS-CoV-2 at 24 hours post-infection, compared to virus-free Caco-2 cells." (PMID 35601094, 2022). "We stably re-expressed orthologous E-cadherin (Cdh1) in a CRISPR/Cas9-mediated cdh1 knockout cell line to investigate E-cadherin shedding upon infection using H. pylori wildtype, an isogenic htrA deletion mutant, or complemented mutants as bacterial paradigms." (PMID 35327548, 2022). "While IPNV has been shown to bind to cdh1, it is unlikely that this is the sole route of entry during infection." (PMID 34547402, 2021). "While it is plausible that cdh1 plays a role in IPN resistance at the site of infection in vivo (e.g. in gut epithelia), the results presented herein do not support a major role for cdh1 in IPN resistance." (PMID 34547402, 2021). "Immunofluorescence staining of infected cells (4 days post infection, 4 dpi) revealed that CDH1 positive cells were found more in OSKME when compared that with OSKM." (PMID 29445086, 2018). "The increase in DNA methylation from 12.8% in control cells to 21.8% after Ct infection should be critically important for E-cadherin expression, as it has been shown that a sharp decline in CDH1 expression occurs above 15% of promoter methylation." (PMID 28660176, 2017). "HRM data revealed an increase from 12.8 to 21.8% after Ct infection, suggesting that the CDH1 promoter region undergoes alterations in DNA methylation in HCjE cells as a result of Ct infection." (PMID 28660176, 2017). "Infection with Ct significantly reduced CDH1 expression; the CDH1 mRNA level was 2.7-fold higher in control than in Ct-infected HCjE cells." (PMID 28660176, 2017). "After Lenti-Cdh1 infection, Cdh1-GFP was observed in nucleus whereas, when infected with Lenti-control, GFP was primarily localised to the cytosol." (PMID 26364211, 2015). "pylori infection experiments, showing that Ni2+ potentiated HtrA-mediated CDH1 shedding." (PMID 41750319, 2026). "Even though we have not analyzed the activity of host proteases in mucosoids of healthy donors in this study, we assume that these host proteases play only a minor role since inhibition of MMPs and ADAM proteases revealed that H. pylori HtrA is the main protease targeting Cdh1 during infection." (PMID 39000189, 2024).
infection (continued). "It is triggered by several factors, both pathogenic, such as infection with Helicobacter pylori, and non-pathogenic, such as mutations of the E-cadherin gene (CDH1), genetic factors, interleukin gene polymorphisms, poor diet, and smoking." (PMID 39684626, 2024). "Under infection conditions, we observed a reduction of E-cad expression at the cell surface that is likely due to cleavage of the extracellular fraction of the protein, as its concentration in the supernatant is continuously increasing over time and the CDH1 gene is overexpressed." (PMID 37285354, 2023). "Moreover, we observed that CD8+ Trm cells expressed higher levels of Itgae (CD103) and Cdh1 at D14 after infection compared to D7." (PMID 37415817, 2023). "Our objective was also to confirm the physiological relevance of the Caco-2 cells cellular model by analyzing the basal expression of the CDH1/E-cad gene to ensure that it was sufficiently expressed in those cells to be able to quantify a possible down modulation of this gene after infection." (PMID 35601094, 2022). "Moreover, in this intranasal infection model, increased mRNA levels of Cdh1 (E-cadherin), Tjp1 (ZO-1), Cldn4 (claudin 4), Cldn5 (claudin 5), and Cldn18 (claudin 18) were observed after IFN-β treatment." (PMID 36559113, 2022). "The infection progression associated with essential epigenetic modifications in two strains of C. albicans such as ARRB2, CDH1, HSP90B1, EGFR and ERBB2, and host miRNA repressing on pathogens genes are mostly identified in core HPCNs by our systems biology approach." (PMID 30769958, 2019). "Infection of HOKs with P. gingivalis, the key periodontal pathogen, significantly downregulated OCLN, CLDN1, and CDH1." (PMID 41358003, 2025). "Mechanistically, HAstV-induced EMT is driven by transcriptional changes; specifically, the downregulation of CDH1 and OCLN and the upregulation of the key transcriptional factor SNAI1 early after infection." (PMID 35452499, 2022). "Using lentiviral infection of AGS cells, we stably restored wild-type CDH1, and observed the expected reversal of the more mesenchymal phenotype seen in V5-alone controls." (PMID 35798764, 2022). "To monitor the difference of LC3B fluorescent spot formation, we performed a secondary infection in FaDu-EGFP-LC3B and HN6-EGFP-LC3B cells with CDH1i lentivirus to stably knockdown CDH1 expression; control cells were infected with Ctrli lentivirus." (PMID 34294686, 2021). "Genes for epithelial cell markers such as cytokeratins 14, 18 and 19 (KRT14, KRT18, KRT19), E-cadherin (CDH1) and epithelial cell adhesion molecule (EPCAM) showed the highest expression at 0 hpi and decreased post-infection." (PMID 34740333, 2021). "Two days after infection, protein was harvested and expression of KLF4 and its previously reported target, E-cadherin (CDH1), were confirmed." (PMID 32552913, 2020). "Furthermore, additional clinical factors such as infection of H. pylori or Epstein-Barr virus (EBV), CDH1 mutation, and pre-operatory performance status, among others, are not included in the SEER database, and thus could not be brought into the LASSO regression analysis." (PMID 32639946, 2020). "Previous studies indicate that orf19.1816 will induce endocytosis by binding host cell receptors such as ERBB2, HSP90B1, CDH1 and CDH2 so that it will be considered as an infection initiation." (PMID 30769958, 2019). "In response to pathogen infection, the receptors such as EGFR, ERBB2, CDH1, HSP90B1, and TJAP1 at the host membrane interact with pathogen cell wall proteins to start inducing endocytosis." (PMID 30769958, 2019).
infection (continued). "E-cadherin (CDH1), the ligand for the inhibitory NK receptor KLRG-1 (killer cell lectin-like receptor subfamily G member 1), was dramatically upregulated during infection." (PMID 24906157, 2014). "Logistic regression analysis for the methylation subset as a whole showed that infection with HPV-18 [P = 0.028], -52 [P = 0.007] or -58 [P <0.001] and promoter methylation of DAPK or CDH1 [P < 0.01] were predictive of HR-HPV infection at follow-up." (PMID 25367268, 2014). "Two to three weeks after infection, the expression of low abundant LEF1 as well as highly expressed CDH1 remained essentially unaffected by GFP-ZBP1." (PMID 23677615, 2013). "The ability of Fn to invade epithelial cells via FadA binding to CDH1 (E- cadherin) and to promote inflammation and oncogenic signalling has been demonstrated using HCT116 xenograft mice and Fn infection in an ApcMin/+ mouse model lead to the generation of a proinflammatory microenvironment." (PMID 33937029, 2021). "In the infection progression of C. albicans SC5314, orf19.1816 (ALS3) plays a significant role in cell adhesion and endocytosis induction by interacting with EGFR, ERBB2 (HER2), CDH1 (E-cadherin), HSP90B1 and TJAP1 (TJP4)." (PMID 30769958, 2019). "Recently, the UL97 kinase of HCMV has been shown to phosphorylate Cdh1 and partially inhibit the APC during infection but with unknown consequences for viral replication." (PMID 22792066, 2012). "For both genes, the global rate of methylation was higher when the virus was present: 32.4% for RB1 in the presence of HPV vs. 15.3% without virus detection, and 25.0% for CDH1 with HPV and EBV infection vs. 15.3% with no infection." (PMID 26032781, 2015). "Independent of UL97-mediated Cdh1 regulation, HCMV also induces degradation of two APC subunits, APC4 and APC5, leading to the dissociation of the complex during infection." (PMID 22792066, 2012). "The mesenchymal marker vimentin/VIM was repressed by infection (FC, −2.22), whereas common markers of EMT (e.g., CDH1/2, SNAI1/2, and ZEB1/2) were not differentially expressed, suggesting that infection does not induce EMT in endocervical epithelial cells at 24 hpi." (PMID 37874141, 2023). "By contrast, P. gingivalis did not degrade CDH1, DSC2, or NECTIN1 at 1 h after infection." (PMID 31697789, 2019). "During infection, human cytomegalovirus (HCMV), a widespread pathogen, not only phosphorylates the APC coactivator Cdh1 via the multifunctional viral kinase pUL97, it also promotes degradation of APC subunits via an unknown mechanism." (PMID 22792066, 2012).
adenocarcinoma (110 papers, 1992 to 2026). A common cancer characterized by the presence of malignant glandular cells. "Changes towards a mesenchymal phenotype were not uniform on GC-derived cell lines, being more noticeable on MKN-45, which is in accordance with its features as a poorly differentiated adenocarcinoma cell line with a mutation on the CDH-1 promoter region." (PMID 34452195, 2021). "KRAS, ARID1A, ABL1, ATM, RET, and CDH1 mutations have been detected in the mesonephric adenocarcinomas containing sex cord-like pattern; among these genes, KRAS mutation was the most frequent." (PMID 31739799, 2019). "miR-9-5p activates N-cadherin by acting on Twist1 to promote EMT in cervical squamous cells, and promotes EMT in adenocarcinoma cells by inhibiting cadherin 1 (CDH1) and activating cadherin 2 (CDH2)." (PMID 35805066, 2022). "The CDH1+/EPCAM+ epithelial cells were enriched in adenocarcinoma and adenosquamous tissues but rarely noticed in NET, in which the EPCAM+/INSM1+ neuroendocrine cells were exclusively identified." (PMID 34185421, 2021). "Currently there is no way of determining the latent period between the intramucosal CDH1 −/− adenocarcinoma and invasion into submucosa." (PMID 21331337, 2011). "We also performed an in vitro investigation on the effect of lncCDH5-3:3 silencing and overexpression on the cell cycle, proliferation, apoptosis, and expression of CDH1 and EPCAM in the adenocarcinoma and squamous cell carcinoma cell lines." (PMID 35159188, 2022). "Previous studies have shown that abnormal methylation patterns of genes (APC, CdH1, CDKN2A, and ESR1) are not only limited to adenocarcinoma tissues but also found in precancerous BE tissues." (PMID 34222478, 2021). "Heatmap analysis revealed upregulated VIM and PLK1 mRNA expression in TGF-β-treated adenocarcinoma when the mesenchymal markers CDH2, SNAI1, and SNAI2 were high and either CDH1 or OCLN (epithelial markers) was low in majority of LUAD cells analysed." (PMID 33963314, 2021). "LOH of the 16q22.1 region, where the CDH1 gene is located, is already described in different types of tumors, such as adenocarcinoma, nonseminoma, gallbladder, breast, endometrial, ovarian, prostate, and various gastrointestinal cancers." (PMID 33915799, 2021). "In contrast, some genes related to the “epithelial-mesenchymal transition (EMT) process” and the “stem cell properties”, including RNF43, CDH1, and SMAD4, as well as the related TGF-β signaling pathway have been observed more frequently altered in SRCC than in conventional adenocarcinoma (AC)." (PMID 34381313, 2021).
breast (32 papers, 2005 to 2026). "Thus, the eight gene panel (CXCL12, CK7, CDH1, CTNNB1, CD44v6, MUC16, TGFBR2 and HIF1A) can be a highly significant predictor of liver metastasis outcome independent of the standard prognostic criteria." (PMID 30383826, 2018).
benign tumors (18 papers, 2007 to 2025). "Analyzing mammary samples according to “tissue group”, benign neoplasms from diestrous bitches expressed significantly higher levels of CDH-1 mRNA than benign neoplasms from spayed or anestrous dogs (p = 0.003 and p = 0.026, respectively)." (PMID 26370564, 2015). "In dogs, CDH-1 can be used as a prognostic factor; its expression, however, in benign tumors is influenced by cycle stage." (PMID 26370564, 2015).
bacterial infection (15 papers, 2016 to 2025). "Moreover, the intracytoplasmic cell concentration of β-catenin (β-cat), a ligand of E-cad, was reduced after bacterial infection, suggesting that the bacterium induces modulation of the E-cad/β-cat signaling pathway and CDH1 and CTNNB1 genes transcription." (PMID 37285354, 2023).
inflammation (10 papers, 2016 to 2025). Aberrant reaction of the microcirculation characterized by movement of fluid and leukocytes from the blood into extravascular tissues. "We previously demonstrated that homozygous Cdh1 knockout in prostate luminal epithelial cells induced prostatic inflammation and hyperplasia and subsequent bladder overactivity in mice at 6 months of age." (PMID 35361739, 2022).
kidney disease (10 papers, 2012 to 2023). "With our study we confirmed that the CDH1 has the potential to serve as an early diagnostic/prognostic marker for diabetic patients at risk of developing kidney disease." (PMID 32121033, 2020). "Seven of those renal disease-related proteins had higher weighted scores (> 0.60), including Ggt1 (0.941), Camp (0.906), Cdh1 (0.835), Lpo (0.833), Scpep1 (0.803), Anpep (0.644), and Ptgds (0.603)." (PMID 33981220, 2021).
neurodegenerative disease (6 papers, 2016 to 2022). A disorder of the central nervous system characterized by gradual and progressive loss of neural tissue and neurologic function. "Interestingly, growing evidence suggests that dysregulation of APC/C-CDH1 is involved in neurodegenerative diseases, potentially as a consequence of amyloid-β driven proteasome-dependent degradation of CDH1." (PMID 31247897, 2019).
hematologic malignancies (4 papers, 2020 to 2025). "Incidental findings of P/LP germline variants in genes associated with non-hematologic malignancies were seen in seven patients, including heterozygous MUTYH G396D identified in four patients, MITF E419K in two, and a CDH1 loss-of-function in one patient." (PMID 39975890, 2025).
metabolic disease (2 papers, 2013 to 2020). A congenital disorder (due to inherited enzyme abnormality) or acquired (due to failure of a metabolically important organ) disorder resulting from an abnormal metabolic process. "Overall, we show that PAH is a prognostic marker for HCC and Cdh1 could be a potential therapeutic target to regulate PAH-mediated physiological and metabolic disorders." (PMID 33260674, 2020).
respiratory diseases (2 papers, 2021). "E-cadherin (CDH1) plays a critical role in the epithelial cell barrier functions and loss of E-cadherin function can lead to respiratory disorders." (PMID 34943813, 2021).
central nervous system disease (1 paper, 2015). "CDH1 plays an important role in the development of central nervous system disease, we deduce the gene CDH1 is correlated with AD." (PMID 26621834, 2015). "CDH1 is important to the development of central nervous system disease." (PMID 26621834, 2015).
neurodevelopmental disorder (1 paper, 2020). A behavioral and cognitive disorder with onset during the developmental period that involves impaired or aberrant development of intellectual, motor, or social functions. "While further studies will be necessary to definitively understand the phenotype-genotype correlations, CTNND1, and perhaps CDH1, should be considered when patients present with characteristic craniofacial anomalies, congenital cardiac defects and neurodevelopmental disorders." (PMID 32196547, 2020).